UFL1 (UFM1 specific ligase 1)
Description:
E3 protein ligase that mediates ufmylation, the covalent attachment of the ubiquitin-like modifier UFM1 to lysine residues on target proteins, and which plays a key role in various processes, such as ribosome recycling, response to DNA damage, interferon response or reticulophagy (also called ER-phagy). As part of the UREL complex, plays a key role in ribosome recycling by catalyzing mono-ufmylation of RPL26/uL24 subunit of the 60S ribosome. Ufmylation of RPL26/uL24 occurs on free 60S ribosomes following ribosome dissociation: it weakens the junction between post-termination 60S subunits and SEC61 translocons, promoting release and recycling of the large ribosomal subunit from the endoplasmic reticulum membrane. Ufmylation of RPL26/uL24 and subsequent 60S ribosome recycling either take place after normal termination of translation or after ribosome stalling during cotranslational translocation at the endoplasmic reticulum. Involved in reticulophagy in response to endoplasmic reticulum stress by mediating ufmylation of proteins such as CYB5R3 and RPN1, thereby promoting lysosomal degradation of ufmylated proteins. Ufmylation in response to endoplasmic reticulum stress is essential for processes such as hematopoiesis, blood vessel morphogenesis or inflammatory response. Mediates ufmylation of DDRGK1 and CDK5RAP3; the role of these modifications is however unclear: as both DDRGK1 and CDK5RAP3 act as substrate adapters for ufmylation, it is uncertain whether ufmylation of these proteins is, a collateral effect or is required for ufmylation. Acts as a negative regulator of T-cell activation by mediating ufmylation and stabilization of PDCD1/PD-1. Also involved in the response to DNA damage: recruited to double-strand break sites following DNA damage and mediates monoufmylation of histone H4 and ufmylation of MRE11. Catalyzes ufmylation of TRIP4, thereby playing a role in nuclear receptor-mediated transcription. Required for hematopoietic stem cell function and hematopoiesis (By similarity).
Synonyms: KIAA0776; MAXER; NLBP; RCAD
Tractability: PROTAC: UniProt records ubiquitination sites on it; ubiquitination databases record sites on it; its protein half-life has been measured.
Target class: Enzyme; Transferase
Gene: Protein-coding gene on chromosome 6 (96,521,595 to 96,555,276, forward strand). Ensembl gene ENSG00000014123.
Subcellular location: Endoplasmic reticulum membrane; Cytoplasm, cytosol; Nucleus; Chromosome
Subcellular location (Human Protein Atlas): Endoplasmic reticulum
Pathways (Reactome):
Immune System: Antigen processing: Ubiquitination & Proteasome degradation
Gene Ontology:
Molecular function: protein binding; protein kinase binding; UFM1 ligase activity; UFM1 transferase activity
Biological process: DNA damage checkpoint signaling; DNA damage response; negative regulation of IRE1-mediated unfolded protein response; negative regulation of protein ubiquitination; negative regulation of T cell activation; negative regulation of T cell mediated immune response to tumor cell; osteoblast differentiation; positive regulation of cell population proliferation; positive regulation of protein catabolic process; positive regulation of reticulophagy; protein K69-linked ufmylation; protein stabilization; protein ufmylation; regulation of intracellular estrogen receptor signaling pathway; regulation of proteasomal ubiquitin-dependent protein catabolic process; regulation of protein localization; rescue of stalled ribosome; response to endoplasmic reticulum stress; reticulophagy; ribosome disassembly; erythrocyte differentiation; hematopoietic stem cell differentiation; positive regulation of autophagy; regulation of canonical NF-kappaB signal transduction; regulation of inflammatory response
Cellular component: chromosome; cytoplasm; endoplasmic reticulum; endoplasmic reticulum membrane; membrane; mitochondrial outer membrane; nucleus; protein-containing complex; site of double-strand break; transferase complex; cytosol; neuron projection
Genetic constraint (gnomAD): Loss-of-function variants: 48 observed, 67.8 expected, observed/expected ratio (o/e) 0.71, 90% interval 0.56 to 0.9. The upper end of that interval is the gene's LOEUF score, 0.9, which puts it in group 3 of 6, group 1 being the genes least tolerant of losing a copy. Missense variants: 763 observed, 776.05 expected, observed/expected ratio (o/e) 0.98, 90% interval 0.93 to 1.04. Synonymous variants: 285 observed, 273.6 expected, observed/expected ratio (o/e) 1.04, 90% interval 0.94 to 1.15.
Homologues: Orthologues: chimpanzee UFL1 (99% identical), macaque UFL1 (99% identical), rabbit UFL1 (94% identical), dog UFL1 (94% identical), rat Ufl1 (91% identical), mouse Ufl1 (91% identical), pig UFL1 (90% identical), guinea pig UFL1 (85% identical), tropical clawed frog ufl1 (69% identical), zebrafish ufl1 (63% identical), Drosophila melanogaster Ufl1 (35% identical), Caenorhabditis elegans ufl-1 (23% identical).
Diseases named in the same sentence as UFL1 in open-access papers:
UFL1 is named in the same sentence as 53 diseases in open-access papers, as found by Europe PMC text mining. Sharing a sentence is not in itself a finding about the gene and the disease. The quoted sentences say what the papers report.
migraine (7 papers, 2016 to 2025). "While, four of these (ICA1L, TREX1, STAT6, and UFL1) have been previously reported in association with migraine." (PMID 37592229, 2023). "UFL1 (UFM1 specific ligase 1) is a novel migraine risk gene involved in ufmylation, a post-translational modification on lysine residues of proteins, that may play a crucial role in a number of cellular processes." (PMID 31917787, 2020). "This suggests UFL1 as a potential target gene for antihistamines targeting the H4 receptor for migraine prevention and treatment." (PMID 37592229, 2023). "Our cell-specific analysis shows UFL1 enrichment in oligodendrocytes and neurons, involved in neuroexcitatory signal regulation and protein modifications in migraine." (PMID 37592229, 2023). "We found significant associations with migraine for 47 genes, with the strongest association for STAT6 (P = 1.24 × 10−23), followed by UFL1 (P = 7.26 × 10−19), and FHL5 (P = 1.25 × 10−18)." (PMID 34294844, 2021). "Our novel findings also implicate UFL1 and ZBTB39 in migraine chronification - UFL1 stabilizes inflammatory proteins, and ZBTB39 epigenetically modifies pain-related genes." (PMID 40826382, 2025). "Five genes, including ICA1L, TREX1, STAT6, UFL1, and B3GNT8, showed significant correlation with migraine in both the proteome and transcriptome." (PMID 37592229, 2023). "The association of modules A–E with migraine may be the result of low migraine association signals, and may therefore not have a direct link to the genome-wide significant GWAS loci, as only module B (LRP1) and module D (UFL1) contain a high-confidence gene." (PMID 26899160, 2016).
hepatocellular carcinoma (6 papers, 2011 to 2025). A malignant tumor that arises from hepatocytes. "To determine if the UFMylation E3 ligase complex protein UFL1 regulates orthoflavivirus infection, we examined the production of infectious virions during DENV or ZIKV infection following siRNA-mediated depletion of UFL1 in human hepatoma Huh7 cells." (PMID 40459261, 2025). "Differences in cancer types and substrates may partly explain the conflicting roles of UFL1 in hepatocellular carcinoma and lung cancer." (PMID 35884562, 2022). "Despite the tumor suppressor role of UFL1 in hepatocellular carcinoma, it may function as an oncogenic gene in lung cancer, specifically, lung adenocarcinoma." (PMID 35884562, 2022). "Additionally, UFL1 was identified as a tumor suppressor in hepatocellular carcinoma through preventing cell invasion, inhibiting NF-kB signaling and increasing the stability of the LZAP protein, implying a critical role of UFL1 in the pathogenesis of HCC." (PMID 35884562, 2022). "It has also been reported that the expression of UFL1 (also called NLBP, RCAD, and Maxer) cannot be detected in invasive hepatocellular carcinoma cells including HepG2, Hep3B, HLE, and PLC, whereas it can be detected in non-invasive Huh7 hepatocellular carcinoma cell line." (PMID 25852645, 2015).
heart failure (4 papers, 2023 to 2024). Inability of the heart to pump blood at an adequate rate to meet tissue metabolic requirements. "The deletion of UFL1 in cardiomyocytes and intestinal epithelial cells caused heart failure and an increased susceptibility to experimentally-induced colitis, respectively, suggesting that UFL1 has an essential role in the maintenance of homeostasis in these organs." (PMID 37947621, 2023). "A recent study reported that Ufl1, a key enzyme of UFMylation, protects against heart failure, indicating that UFMylation may be associated with heart function regulation." (PMID 37980507, 2023). "We also found a significant decrease in UFL1 in the heart of both mouse models, which is consistent with a previous report that Ufl1 is downregulated in human failing hearts, and it can protect against heart failure." (PMID 39858578, 2024). "Cardiac–specific ablation of UFL1 led to heart failure with a concomitant reduction of UFBP1, implying a possible role of UFBP1 in the heart." (PMID 37566002, 2023).
colitis (3 papers, 2019 to 2023). Inflammation of the colon. "Ablation of either Ufl1 and Ufbp1 led to significant loss of both Paneth and goblet cells, which in turn resulted in dysbiotic microbiota and increased susceptibility to experimentally induced colitis." (PMID 30701081, 2019). "Using both acute and tissue-specific knockout mouse models, we found that ablation of either Ufl1 or Ufbp1 led to significant loss of Paneth and goblet cells, which in turn resulted in dysbiotic microbiota and increased susceptibility to experimentally induced colitis." (PMID 30701081, 2019). "Intestinal epithelial–specific UFL1 and UFBP1 knockout mice were more susceptible to experimentally induced colitis." (PMID 37566002, 2023).
lung carcinoma (3 papers, 2015 to 2025). "We observed similar results in A549 cells, a lung carcinoma line susceptible to orthoflavivirus infection, where depletion of either UFL1 or UFBP1 decreased the production of infectious ZIKV virions and resulted in reduced expression of both proteins." (PMID 40459261, 2025). "In addition, UFL1 is highly expressed in human lung adenocarcinoma and its overexpression promotes the proliferation of rat H1299 lung cancer cells through interaction with p120 catenin, suggesting that UFL1 may play a role in development of lung carcinoma." (PMID 25852645, 2015).
melanoma (3 papers, 2022 to 2025). A malignant, usually aggressive tumor composed of atypical, neoplastic melanocytes. "In melanoma patients, low levels of UFL1 expression in tumor tissues are significantly associated with poor responses to anti-PD-1 immunotherapy." (PMID 41179291, 2025). "For instance, a melanoma patient with low UFL1 expression is closely associated with high PD-L1 expression." (PMID 41179291, 2025). "Similar to GC, CDK5RAP3 and UFL1 also play a tumor suppressing role in renal carcinoma and melanoma, respectively." (PMID 41179291, 2025). "Reduced UFL1 levels were observed across several cancers, and lower UFL1 expression was associated with a diminished response to anti-PD1 therapy in melanoma patients." (PMID 38638430, 2024). "Furthermore, by using RNA-seq data from The Cancer Genome Atlas (TCGA) melanoma cohort, we found that the mRNA level of UFL1 was negatively correlated with those of well-known targets downstream from melanin biosynthesis pathway, including OCA2 and SLC45A2." (PMID 36120581, 2022).
anemia (2 papers, 2016 to 2024). A reduction in the number of red blood cells, the amount of hemoglobin, and/or the volume of packed red blood cells. "Deletion of RCAD/UFL1 significantly impairs hematopoietic development, leading to severe anemia, cytopenia, and eventual lethality." (PMID 39247188, 2024). "Additionally, Ufl1 knockout in mice compromised HSC survival, and tamoxifen-induced somatic knockout of Ufl1 in mice resulted in death due to severe anemia." (PMID 27212118, 2016). "Recent investigations have demonstrated that Ufl1 knockout mice die in utero due to severe anemia." (PMID 27212118, 2016).
diabetes (2 papers, 2021 to 2023). "A limitation of the present study is the lack of detailed data on the function of Ufl1 or Ufbp1 in obesity and diabetes, which is critical to fully understand the novel role of these proteins in human disease." (PMID 37131258, 2023).
fatty liver (2 papers, 2023 to 2024). "Collectively, results from these analyses suggest that Ufl1 or Ufbp1 deletion increases the susceptibility to HFD-induced fatty liver." (PMID 37131258, 2023). "We next explored the association of hepatic Ufl1 or Ufbp1 deficiency with the susceptibility to HFD-induced fatty liver." (PMID 37131258, 2023).
liver fibrosis (2 papers, 2023 to 2024). "Ufl1 and Ufbp1 play critical roles in preventing liver fibrosis, steatohepatitis, and HCC by acting as inhibitors of the mTOR pathway, highlighting their potential as therapeutic targets for liver diseases." (PMID 39247188, 2024). "Ufl1 and Ufbp1 prevent liver fibrosis, steatohepatitis, and HCC by inhibition of mTOR." (PMID 39247188, 2024).
lung adenocarcinoma (2 papers, 2015 to 2022). A carcinoma that arises from the lung and is characterized by the presence of malignant glandular epithelial cells. "UFL1 was upregulated in cancerous tissue in the early stages of lung adenocarcinoma, while the overexpression of UFL1 promoted the proliferation of lung adenocarcinoma H1299 cells." (PMID 35884562, 2022).
mastitis (2 papers, 2019 to 2020). Inflammation of breast tissue during lactation or postpartum due to an obstructed duct or infection. "Despite extensive research regarding other proteins involved in the UFM1 system, as well as the importance of UFL1 in mastitis and breast cancer, our knowledge of UFL1 function in the mammary gland requires further elucidation." (PMID 32655766, 2020). "Additional support for the idea that UFL1 is involved in bovine mastitis was provided by experiments in which UFL1 was overexpressed." (PMID 30881595, 2019). "To further investigate the possible involvement of UFL1 in bovine mastitis, we downregulated UFL1 expression in BMECs using small interfering RNA, and the results showed that UFL1 siRNA could suppress the expression of UFL1 mRNA and protein." (PMID 30881595, 2019). "The ability of UFL1 to regulate inflammation in vitro suggests that UFL1 could be a potential therapeutic target for bovine mastitis." (PMID 30881595, 2019).
Obesity (2 papers, 2023 to 2024). Accumulation of substantial excess body fat. "As expected, the expression levels of hepatic Uba5, Ufc1, Ufl1, and Ufm1 are significantly reduced in patients with obesity, MASLD, and MASH by analyzing the public data sets." (PMID 39858578, 2024).
osteoarthritis (2 papers, 2022 to 2025). A noninflammatory degenerative joint disease occurring chiefly in older persons, characterized by degeneration of the articular cartilage, hypertrophy of bone at the margins and changes in the synovial membrane. "Recently, it was reported that panaxatriol can target UFL1 to exert anti-aging effects, and can alleviate fibrosis in osteoarthritis and cartilage repair." (PMID 40572616, 2025). "In recent years, studies have shown that UFL1 can protect cells, such as bovine mammary epithelial cells, goat endometrial epithelial cells and human osteoarthritis chondrocytes, from LPS stimulation." (PMID 35610622, 2022).
prostate carcinoma (2 papers, 2022 to 2026). A carcinoma that arises from epithelial cells of the prostate gland. "UFL1 deficiency enhances prostate cancer cell resistance to ENZ both in vitro and in vivo." (PMID 41608626, 2026).
spinocerebellar ataxia type 1 (2 papers, 2014 to 2016). Spinocerebellar ataxia type 1 (SCA1) is a subtype of type I autosomal dominant cerebellar ataxia (ADCA type I) characterized by dysarthria, writing difficulties, limb ataxia, and commonly nystagmus and saccadic abnormalities. "Ufl1 was shown to be involved in the neurodegenerative disorder, spinocerebellar ataxia type 1 (SCA1), which belongs to the polyglutamine diseases." (PMID 24921187, 2014).
acute kidney injury (1 paper, 2024). Sudden and sustained deterioration of the kidney function characterized by decreased glomerular filtration rate, increased serum creatinine or oliguria. "Our study further corroborates these findings, showing a reduction in DDRGK1, UFL1, and UFM1 in acute kidney injury, which suggests a decrease in ER-phagy." (PMID 38233375, 2024).
alcoholic hepatitis (1 paper, 2023). Acute hepatitis resulting from ingestion of alcohol. "Ufm1 members have also been shown to be downregulated in alcoholic hepatitis and cirrhosis biopsies, and Ufl1 and Ufbp1, particularly, are suggested to act as tumor suppressors in certain cancers." (PMID 37131258, 2023).
autoimmune disease (1 paper, 2023). A disorder resulting from loss of function or tissue destruction of an organ or multiple organs, arising from humoral or cellular immune responses of the individual to their own tissue constituents. "Our confocal assay proved that UFL1 interacts with STING under the unstimulated condition which means the combination of UFL1 and STING is constitutive, it may provide a new therapeutic target for inhibiting autoimmune disease triggered by abnormally activated STING." (PMID 35871231, 2023).
Autoimmunity (1 paper, 2023). The occurrence of an immune reaction against the organism's own cells or tissues. "Our study reveals a novel non-classical mechanism that the E3-like ligase UFL1 can maintain the expression of STING independent of UFMylation, which provides new strategy to improve antiviral therapy and to regulate self-DNA triggered autoimmunity." (PMID 35871231, 2023).
Bovine mastitis (1 paper, 2019). INFLAMMATION of the UDDER in cows. "Collectively, UFL1 may play an important role during the inflammatory response and thereby acts as a potential therapeutic target for bovine mastitis." (PMID 30881595, 2019). "UFL1 has recently been identified as an important regulator of the cellular stress response, but no studies have addressed the effect of UFL1 on BMECs, and the role of UFL1 in bovine mastitis is still unknown." (PMID 30881595, 2019).
breast carcinoma (1 paper, 2020). "It was previously found that UFL1 interaction with UFM1 is critical for the UFMylation of activating signal cointegrator 1 under estrogen to inhibit breast cancer growth." (PMID 32655766, 2020).
cardiac hypertrophy (1 paper, 2024). "For instance, in mouse models of transverse aortic constriction-induced cardiac hypertrophy, both UFL1 and UFM1 are upregulated, activating protein UFMylation." (PMID 38233375, 2024).
cardiomyopathy (1 paper, 2022). A disease of the heart muscle or myocardium proper. "Mechanistically, UFL1 exerted a protective role on the pathogenesis of cardiomyopathy via regulating PERK signaling and consequently cardiomyocyte cell death." (PMID 35884562, 2022). "Meanwhile, cardiac specific Ufl1-knockout mice developed cardiomyopathy and heart failure." (PMID 35884562, 2022).
diffuse large B-cell lymphoma (1 paper, 2016). "However, despite the amplification of UFC1 in pancreatic adenocarcinoma and amplification of both UFC1 and UFL1 in diffuse large B-cell lymphoma, high percentage of UFL1 deletion and UFL1/UFM1 deletion was also detected in pancreatic adenocarcinoma and diffuse large B-cell lymphoma, respectively." (PMID 27212118, 2016).